RNU6-750P (RNA, U6 small nuclear 750, pseudogene)
Gene: Small nuclear RNA gene on chromosome 1 (99,978,939 to 99,979,045, forward strand). Ensembl gene ENSG00000212248.
Homologues: Orthologues: chimpanzee U6 (97% identical), rabbit U6 (76% identical), dog U6 (74% identical), rat LOC120095355 (64% identical). Paralogues in human: RNU6-742P (84% identical), RNU6-1209P (83% identical), RNU6-11P (80% identical), RNU6-15P (80% identical), RNU6-216P (80% identical), RNU6-37P (80% identical), RNU6-1 (79% identical), RNU6-1042P (79% identical), RNU6-10P (79% identical), RNU6-1145P (79% identical), RNU6-1287P (79% identical), RNU6-1309P (79% identical), and 1284 more.